IL4 (interleukin 4)
Diseases named in the same sentence as IL4 in open-access papers (continued):
Sharing a sentence is not in itself a finding about the gene and the disease.
eosinophilia (continued). "In studies of the immunomodulatory function of ESPs, helminths have been shown produce ESPs to induce the generation of Th2 cytokine (IL-4, IL-10, and IL-13) by the host, inflammation, and the elevation of IgE and eosinophilia levels in the serum." (PMID 32479527, 2020). "Elevated numbers of Th2 cells, an overproduction of IL-4 and IL-5, and elevated serum IgE as well as eosinophilia were found in some of these patients." (PMID 33126494, 2020). "To date, the presence and degree of type 2 inflammatory responses, involving eosinophilia and increased levels of the proinflammatory cytokines IL-4, IL-5, and IL-13, have been the focus of asthma research." (PMID 33101299, 2020). "In a murine model for OVA-induced asthma, i.p. lycopene injections of sensitized mice for 3 days before OVA challenge lowered AHR and eosinophilia for 50%, while normalizing IL-4 levels in the BALF and increasing IFN-γ, indicating a shift in T-cell response." (PMID 32973501, 2020). "During a classic type 2 immune response, IL-4 promotes B cell antibody class switching to immunoglobin E (IgE), IL-5 recruits eosinophilia to the inflammation sites, and IL-13 promotes mucus production and goblet cell hyperplasia." (PMID 33126494, 2020). "Oral administration of 100 mg/kg extract caused 86% inhibition of eosinophilia, reduction of TH2 cytokines (IL-4, IL-5, IL-13) and TNF-α level in BALF and decreased serum IgE level in ovalbumin-sensitized mice." (PMID 31275149, 2019). "The increased levels of IL-4/IL-13 and serum IgE as well as mast cell accumulation, led us to predict the occurrence of eosinophilia." (PMID 30654796, 2019). "Th2 cells migrated to the lung secrete the prototypical Th2 type cytokines IL-4, IL-5, and IL-13, resulting in goblet cell hyperplasia, bronchoconstriction, and eosinophilia in the airway." (PMID 29991953, 2018). "Eosinophilic asthma is characterized by Th2 cell activation, IL-4, IL-5, and IL-13 production, high IgE levels and strong eosinophilia." (PMID 30534125, 2018). "Exogenous IL-4 delivery recapitulated tissue AAMφ expansions, sustained eosinophilia and mediated immunological resistance in Mφ-intact SCID mice." (PMID 29547639, 2018). "The present data are in agreement with other studies, which demonstrated that, during the T. canis infection, the eosinophilia is followed by a significant increase in plasmatic IL-4 levels." (PMID 29445372, 2018). "As is observed in human LF, B. malayi infected ferrets exhibit an initial mixed Th1/Th2 immune response, as evidenced by increased cytokine transcription (IL-4, IFNγ) and peripheral eosinophilia, followed by later evidence of immunoregulation." (PMID 29601572, 2018). "Serum IL-4, IL-5, and IL-6 levels increased in the present case when MM developed with eosinophilia, and these cytokines and eosinophils decreased after the treatment of MM." (PMID 30376895, 2018). "These are typically characterized by increased expression of cytokines such as interleukin-4 (IL-4), IL-13, eosinophilia, production of immunoglobulin E (IgE), and stimulation of alternatively activated (M2) macrophages and type 2 innate lymphoid cells (ILC2)." (PMID 30467504, 2018). "Among the main cytokines produced on the eosinophilia peak (18th day), IL-4 showed a significant increase in the INF group when compared with the NI group." (PMID 29445372, 2018). "T-helper 2 (Th2) associated responses, such as production of interleukin 33 (IL-33), (interleukin 13) IL-13, (interleukin 4) IL-4 cytokines, and eosinophilia, are generally considered to be detrimental." (PMID 29463005, 2018). "In our study, among the three doses, the high dose of compound 8a (5 mg) obviously reduced the expression of IL-4, contributing to the best protective effect on airway eosinophilia and trafficking of activated T cell into airway in asthmatic mice." (PMID 29118379, 2017).
eosinophilia (continued). "Induction of eosinophilia is due to Type-2 cytokines IL-4 and IL-5 produced by Th2 and ILC2 cells in response to the parasitic infection." (PMID 29163523, 2017). "Confirming these observations, blocking CD86 decreased Th2 immune responses, demonstrated by low IL-4 and IL-5 cytokines as well as low airway eosinophilia." (PMID 29333430, 2017). "Intravenous injection of a recombinant adeno-associated virus containing the IL-4 ASO (rAAV-asIL4) vector significantly suppressed airway inflammation, particularly eosinophilia in an OVA-challenged lung inflammation rat model." (PMID 28106744, 2017). "TPL-2 deficiency led to exacerbated HDM-induced airway allergy, with increased airway and tissue eosinophilia, lung inflammation, and IL-4, IL-5, IL-13, and IgE production." (PMID 27484038, 2017). "IVE and AET treatment also decreased IL-4 and IL-13 mRNA expression in lung tissue, as well as eosinophilia and IL-4, IL-5, and IL-13 production in BALF." (PMID 29062168, 2017). "Inflammation in AD is mediated by an initial Th2 phase, which is orchestrated by IL-4, IL-5, and IL-13 cytokines and is related to IgE production and eosinophilia." (PMID 28265582, 2017). "M. tuberculosis infection inhibited OVA-induced lung allergic responsessuch as eosinophilia, IL-4 and IL-5 production." (PMID 28128217, 2017). "In the absence of a hematological malignancy, the Th2-type cytokine interleukin-5 (IL-5) is critical for the development of a peripheral eosinophilia whilst B lymphocyte class-switching to IgE synthesis is dependent on the Th2-type cytokines IL-4/IL-13." (PMID 28506264, 2017). "Treg-depleted mice showed increased mucus production, eosinophilia, IgE production, Th2 cytokines (IL-4, IL-5, IL-13), as well as increased fungal burden." (PMID 29333430, 2017). "In rats, N. brasiliensis infection induces eosinophilia and Th2 cytokines IL-4 and IL-5 between 7 and 14 days, after which these parameters return to normal by 28 days due to expulsion of the parasites." (PMID 29163523, 2017). "Over-production of TH2-related cytokines (IL-4, IL-13, and IL-5) in IgG4-RD tissues has previously been reported and correlates with IgE and IgG4 class switch, blood eosinophilia, and eosinophilic infiltrates that are common features of IgG4-RD." (PMID 28348556, 2017). "IL-4 is involved in induction of airway hyperresponsiveness and production of specific IgE and T cell-derived IL-5 is one of the key regulators of eosinophilia in lungs." (PMID 27795621, 2016). "It has been demonstrated that helminth infections strongly induce an immune response involving elevated Th2 cytokines (i.e., IL-4, IL-5, IL-9, and IL-13), IgE, IgA, eosinophilia, and mucus secretion." (PMID 27882241, 2016). "AD is often a T helper 2 (Th2)-mediated disease, accompanied by increased serum total IgE production, circulating interleukin-4 (IL-4)/IL-13-expressing T cells, and eosinophilia (1, –, 3)." (PMID 27981233, 2016). "Airway eosinophilia and the levels of IL-4, IL-5, and IL-13 were attenuated by the anti-CCL3 antibody." (PMID 27829417, 2016). "We observed a reduction of 84% in blood eosinophilia and a decrease in the IL-4 and IL-10 blood levels after treatment." (PMID 27378927, 2016). "Anti-interleukin-4 and anti-interleukin-5 had been effective in reducing exacerbations and persistent eosinophilia in asthmatic patients." (PMID 26101464, 2015). "Then, even with little differences in the production of IL-4 and IL-12 by APCs, both protocols induced significant differences on IL-5 production and eosinophilia." (PMID 25973430, 2015). "IL-13, which shares a receptor component and signaling pathways with IL-4, plays a central role in airway eosinophilia and development of AHR." (PMID 25826377, 2015). "The Th2 immune response is characterized by the development of IL-4 and IL-5-producting effector T cells, which contribute to the allergic responses in several aspects, such as eosinophilia." (PMID 25960757, 2015).
eosinophilia (continued). "On the other hand, inhibition of IL-4 by monoclonal antibodies attenuates airway eosinophilia and IgE level in allergic mice; therefore, the production of IgE is closely related to the concentration of IL-4." (PMID 26035827, 2015). "The allergic reactions to OVA in mouse airway typically evoke TH2 dominated responses with dramatically increased levels of IL-4, IL-5, and IL-13, which are accompanied by eosinophilia and IgE expression." (PMID 24755955, 2014). "We showed here that mev mice had a spontaneous allergic rhinitis-like inflammation with eosinophilia, mucus metaplasia, up-regulation of Th2 cytokines (IL-4 and IL-13), chemokines (eotaxin), and MMPs." (PMID 25090641, 2014). "Those strains able to limit egg production and curtail infection display a suite of enhanced Type 2 responses, including in particular T cell production of IL-4 and IL-10, eosinophilia and alternatively activated macrophages." (PMID 24492801, 2014). "Toxocara infection results in the induction of Th2 cells that make cytokines such as IL-4, IL-5, and IL-13, which induce responses to the parasite such as increased IgE levels and eosinophilia." (PMID 23365718, 2013). "Although this protection was associated with desensitisation of mast cell responses, ES-62 was also shown to suppress the Th2 phenotype of the allergic response, as measured by a reduction in eosinophilia and IL-4 levels in the lungs." (PMID 23291461, 2013). "As expected, mice that received FI-A2 alone developed substantial pulmonary BAL cell infiltration and eosinophilia following A2 challenge, as well as an increased Th2 type IL-4 cytokine response, and increased body weight loss." (PMID 24376637, 2013). "More recently, another filarial nematode-derived molecule, cystatin, has been found to protect against OVA-induced airway hyper-reactivity, showing many of the properties of ES-62 in reducing eosinophilia, IgE and IL-4." (PMID 23291461, 2013). "For instance, eosinophilia is a consequence of the type 2-mediated inflammation and eosinophil expressing IL-4 is an early event during nematode infection." (PMID 23536877, 2013). "Allergic inflammation is characterized by increased Th2 cytokines including IL-4, IL-5, and IL-13 resulting in tissue eosinophilia, epithelial mucus metaplasia, and IgE production." (PMID 24876829, 2013). "The classic paradigm underlying allergic disease has been characterized by allergen specific Th2 cell production of IL-4, IL-5 and IL-13 leading to tissue eosinophilia, mucus production, and specific IgE production." (PMID 24876829, 2013). "Increased secretion of IL-4 and IL-13 by T cells leads to antibody class switching (from IgG to IgE) by B cells, and IL-5 induces eosinophilia." (PMID 23451048, 2013). "OVA-induced mice showed eosinophilia, airway inflammation, mucus hypersecretion, and elevated levels of IL-4, IL-13 and eotaxin in BALF." (PMID 23110404, 2012). "The immune response of the host to worm infection correlates with the production of interleukin 4 (IL-4), IL -5, IL-9, IL-10, and IL-13 and consequently the development of strong Immunoglobulin E (IgE) and eosinophilia." (PMID 22952620, 2012). "Blocking of IL-4 by monoclonal antibodies decreases IgE level and airway eosinophilia in allergic mice." (PMID 23244755, 2012). "Despite the absence of adult forms in humans, TSO clearly induces a strong TH2 response in treated subjects, as indicated by increased serum IL-4, eosinophilia, and IgE antibodies." (PMID 23166490, 2012). "In contrast, FI-PVM immunized mice developed a Th2-skewed response, as indicated by the relatively high levels of IL-4 in the lungs and eosinophilia in two out of four mice." (PMID 22940382, 2012). "While IL-4 overexpression led to eosinophilia and mucus metaplasia, subepithelial fibrosis in IL-4 overexpressing models has been unimpressive or absent depending on the study." (PMID 22315625, 2012).
eosinophilia (continued). "Efforts to understand eosinophilia and the tumor response to IL-4 in rodent models, including studies of GBM, revealed that the release of IL-4 at the tumor site induced significant eosinophil influx, tumor rejection, and the prolonged survival of nude mice." (PMID 22251275, 2012). "IL-4 can directly induce airway hyperresponsiveness and airway and blood eosinophilia in asthmatic patients, and other investigators have shown an inhibitory effect of IFN-γ on pulmonary allergic responses." (PMID 22203879, 2012). "For example, IP-10 overexpression in the lung of a mouse model of allergic airway inflammation increases airway hyperreactivity, eosinophilia, and IL-4 levels." (PMID 22004287, 2011). "Food allergenicity is characterized by abnormal IgE production, peripheral eosinophilia, mast cell activation, and induction of Th2 lymphocytes expressing cytokines such as IL-4 and IL-10." (PMID 22091390, 2011). "We have previously shown this method to induce significant airway hyperresponsiveness to acetylcholine, increased serum IgE, increased eosinophilia and increased Th2 (IL-4, IL-5 and IL-13) cytokine expression." (PMID 22151973, 2011). "In our studies, blockade of IL-10 in conjunction with PZQ treatment led to an increase in eosinophilia and adult worm-specific IL-4, IL-5, IFNγ and IL-17A." (PMID 21829367, 2011). "Eosinophilia is driven by allergen-activated Th2 cells that generate large amounts of Th2 cytokines (such as IL-4, IL-5, and IL-13)." (PMID 21772663, 2011). "The immune response in clinically asymptomatic individuals is dominated by IL-4, IL-5, IL-10, and IL-13 secretion, IgE and IgG4 antibodies, and peripheral eosinophilia." (PMID 19381284, 2009). "Sézary's syndrome (a peripheral T-cell neoplasm) has been associated with elevated IgE and/or eosinophilia when the malignant clone is of the CD4+ helper phenotype and produces an abnormal amount of the cytokine IL-4." (PMID 20016775, 2009). "In animals, IL-33 treatment induces the expression of IL-4, IL-5 and IL-13 in the lung and intraperitoneal injection of IL-33 induces spleen eosinophilia." (PMID 18315837, 2008). "As helminthiasis, atopy is the result of aberrant Th2 cytokine response to allergens, with an increased production of IL-4, IL-13, Il-9 and Il-5, with high amounts of allergen-specific and total IgE and eosinophilia." (PMID 19471606, 2008). "Alternatively, IL-10 or TGFβ support Th2 responses that impact on antibody production, mast cell degranulation and eosinophilia via secretion of IL-4, IL-5, IL-10, IL-13." (PMID 17430585, 2007). "C3-deficient mice challenged with allergen show diminished airway hyperresponsiveness and lung eosinophilia, with dramatic reduction of the number of IL-4-producing cells and attenuation of IgE responses." (PMID 15339344, 2004). "Dupilumab blocks IL-4/IL-13 signaling, targeting key components of the type 2 (T2) inflammatory cascade: it reduces B-cell class switching toward IgE, suppresses effector T2 signals, and decreases tissue eosinophilia and other T2 markers." (PMID 41210306, 2025). "Finally, some authors have questioned the tapering of oral corticosteroids (OCS) as a potential contributor to blood eosinophilia observed during IL‐4/IL‐13 treatment." (PMID 40492692, 2025). "While the IL-4-related mechanism remains speculative, it warrants further investigation, especially in cases with marked eosinophilia or allergic features." (PMID 40666556, 2025). "Its superior performance likely stems from its dual inhibition of IL‐4 and IL‐13 signaling via IL‐4Rα blockade, a mechanism validated in preclinical models where IL‐4Rα knockout mice exhibited reduced mucosal eosinophilia and polyp burden in house dust mite‐induced nasal polyposis." (PMID 41178615, 2025).
eosinophilia (continued). "Atopic asthma is characterized by a Th2-skewed immune response, marked by the activation of Th2 cells that release cytokines such as Interleukin 4 (IL-4), IL-5, and IL-13, which can lead to eosinophilia, mucous production, respiratory inflammation, and airway remodeling." (PMID 40004141, 2025). "In this study, we found that this subgroup exhibited not only an increase in the levels of inflammatory cytokines, such as IL-6 but also a profile indicative of type 2 inflammation, including peripheral blood eosinophilia and elevated serum IL-4 and IL-13 levels." (PMID 40278124, 2025). "IL-4 enhances mucus and IgE production and stimulates mast cells, while IL-5 promotes eosinophilia." (PMID 39421735, 2024). "Furthermore, immunotherapy with interleukin (IL)‐2,31, 32 IL‐4,33 granulocyte‐macrophage colony‐stimulating factor, or tumor vaccines often results in peripheral eosinophilia." (PMID 38087769, 2024). "The basis for atopy may stem from an exaggerated Th2 response involving cytokines such as IL-4, IL-5, and IL-13, as well as eosinophilia." (PMID 38742158, 2024). "A Th2-skewing of T-bet-deficient CD4+ cells may also cause inflammation of the upper respiratory tract, peripheral eosinophilia, and an increase in Th2-cytokines IL-4, IL-5, and IL-13." (PMID 38835658, 2024). "Moreover, in addition to LPS, β-glucans contained in fine matter particles were suggested to exacerbate murine lung eosinophilia paralleled by increased IL-4 and IL-13 production in bronchoalveolar lavage fluid." (PMID 39337403, 2024). "Type 2 inflammation is associated to a greater disease burden and is defined by tissue eosinophilia (≥ 10 eosinophils/high field power, blood eosinophilia (≥ 150 cells/μL and high level of serum total IgE (≥ 100 KU/L) and additional increased expression of T2 cytokines such as IL-4, IL-5, IL-13." (PMID 38913122, 2024). "When assassin lung cytokine modules, no overt Th2 cytokine module was observed in vaccinated and challenged mice exhibiting eosinophilia, a marked difference from small rodent models of VAERD which are characterized by high levels of IL-4, IL-5, and IL-13 and weight loss." (PMID 37600776, 2023). "Additionally, we observed leukocyte morphological changes, eosinophilia, and increased serum levels of IL-2, IL-4, IL-5, and type I and II interferons." (PMID 37766239, 2023). "Furthermore, pharmacological inhibition of IL-6 during airway inflammation was associated with a marked local increase in protein levels of IL-13, IL-4, and IL-5, which are critically involved in Th2-mediated eosinophilia." (PMID 35408882, 2022). "For instance, mice deficient in IL-4 repeatedly exposed to A. fumigatus antigen failed to develop an IgE response but showed comparable lung eosinophilia and lung pathology to that observed in wild-type mice." (PMID 35205913, 2022). "Mice deficient in CD1d-/- and Jα18-/- iNKT cells showed a decrease in airway hyperresponsiveness and eosinophilia, while the adoptive transfer of IL-4- and IL-13-producing iNKT cells restored the airway inflammation, suggesting that type 2 iNKT cells are responsible for asthmatic inflammation." (PMID 35720287, 2022). "However, IL-33 administration can also induce marked type 2 inflammation, with eosinophilia, increased production of the interleukins IL-4, IL-5 and IL-13 as well as mucus production and epithelium remodeling." (PMID 35844529, 2022). "Unbiased single-cell sequencing analysis of controls and SP-CI73T mutants at a time coordinated with peak eosinophilia (14 days) defined heightened inflammatory activation, chemotaxis, and survival signaling (IL-6, IL-4/13, STAT3, Glucocorticoid Receptor, mTOR, and MYC) in eosinophils." (PMID 35571100, 2022). "The same treatment also significantly reduced the expression of genes linked to Th2 response and eosinophilia (Il4 and Il5 but not Il13) as well as eosinophil recruitment (Ccl5 and Ccl11) in Atg7fl/fl;Lyz2‐Cre ECRS mice." (PMID 35988262, 2022).